APLN (apelin)
Diseases named in the same sentence as APLN in open-access papers (continued):
Sharing a sentence is not in itself a finding about the gene and the disease.
diabetes (continued). "In the present study, we aimed to uncover the role of circulatory apelin in type 2 diabetes mellitus (T2DM) patients with mild cognitive impairment (MCI)." (PMID 35610700, 2022). "This study was designed to investigate the role of apelin in type 2 diabetes mellitus (T2DM) patients with mild cognitive impairment (MCI)." (PMID 35610700, 2022). "Of the established apelin isoforms, apelin-13 appears to be the most interesting in terms of diabetes therapy owing to its ability to improve glucose tolerance and insulin sensitivity, as well as potential effects to enhance insulin secretion." (PMID 35177945, 2022). "This review will focus predominantly on recent research on the therapeutic potential of apelin in diabetes." (PMID 35177945, 2022). "Apelin, an adipokine that is upregulated in diabetes mellitus, was reported to improve endothelial cell dysfunction and attenuate cardiac insufficiency induced by ischemia and reperfusion." (PMID 33504680, 2021). "Apelin alleviated diabetic cardiomyopathy via attenuating endothelial cell dysfunction induced by diabetes mellitus, including increasing proliferation, migration, tube formation and decreasing apoptosis, expression of adhesion molecules." (PMID 33504680, 2021). "The results showed that apelin infusion ameliorated cardiac dysfunction in diabetic mice, which means that apelin protected the heart from cardiac dysfunction induced by diabetes mellitus." (PMID 33504680, 2021). "In a mouse model, increased apelin concentrations in plasma inhibited podocyte autophagy leading to podocyte apoptosis and renal dysfunction in diabetes, thus contributing to the progression of DKD." (PMID 34206927, 2021). "Ultrasonic inspection results for the diabetes ischemia reperfusion injury rat models after Apelin therapy." (PMID 33342766, 2020). "Numerous studies have shown that APLN/APLNR polymorphisms are associated with the risk of several diseases such as hypertension, CAD, and diabetes mellitus." (PMID 32849850, 2020). "The study was aimed to investigate the effects of diabetes induction on apelin and APJ gene expression in AT of a well‐established animal model of type 2 diabetes and evaluate the effects of L‐carnitine on AT expression of apelin and APJ gene." (PMID 33278072, 2020). "For example, the adiponectin receptor agonist AdipoRon ameliorates insulin resistance and diabetes in mice, while the use of apelin antagonist diminishes hepatic fibrosis in rats." (PMID 32660156, 2020). "Diabetes accounts for about 15% of total diseases related to selected myokines (apelin, BDNF, IL-15, irisin, SPARC)." (PMID 30984014, 2019). "Nevertheless, the role of the apelin system in relation to diabetes and its complications is still unclear and further investigation is required." (PMID 31492821, 2019). "The apelin–APJ system has become a therapeutic target in the treatment of diabetes and its complications." (PMID 30868058, 2019). "The present study aimed to investigate the roles of PIO and KLF4 in the transcriptional regulation of apelin in a high-fat diet/streptozotocin rat model of diabetes and in PIO-stimulated vascular smooth muscle cells (VSMCs)." (PMID 31829402, 2019). "The role of apelin and its connection with the etiopathogenesis of diabetes-related complications is being increasingly investigated." (PMID 31492821, 2019). "While a study that included patients with diabetes mellitus reported an increase in circulating apelin levels after a CAE program, another investigation showed no change after a similar exercise program." (PMID 29482601, 2018). "In conclusion, our study demonstrated that there was a close relationship between Apelin-13, BMD, ICTP and PINP, suggesting that Apelin-13 plays an important role in the occurrence of osteoporosis in patients with Type-2 diabetes mellitus." (PMID 29643899, 2018).
diabetes (continued). "In conclusion, increased apelin concentration in plasma inhibited podocyte autophagy, which would lead to podocyte apoptosis and renal dysfunction in diabetes." (PMID 28837139, 2017). "Our present study provides direct evidence that Sirt3 has a critical role in apelin-induced myocardial angiogenesis in ischaemic heart of diabetes." (PMID 25311234, 2015). "Using this ischemic STZ mouse model, we have examined the effects of apelin gene therapy on the autophagy and ROS formation in ischemic hearts of diabetes." (PMID 29167823, 2015). "Apelin is adipokine secreted by peripheral tissues but also present in the hypothalamic neurons, having a major impact on the genesis and progression of diabetes." (PMID 26834545, 2015). "Our present findings elucidate a novel mechanism by which apelin protects the ischemic heart of diabetes." (PMID 29167823, 2015). "In this regard, in a study fasting plasma apelin levels correlated positively with IR in patients with type 2 diabetes mellitus, while in another study plasma apelin levels were reduced in newly diagnosed and untreated patients with type 2 diabetes mellitus." (PMID 24757680, 2014). "It is likely that therapies that inhibit the pathway of apelin will form an important component of future therapy in patients with diabetes, acting in conjunction with conventional approaches to prevent DR." (PMID 23874984, 2013). "These adipokines including leptin, visfatin, resistin, apelin, vaspin, and retinol binding protein-4 can regulate inflammatory responses and contribute to the pathogenesis of diabetes." (PMID 23772224, 2013). "Low apelin levels have been detected in patients with high LDL levels and those with type 2 diabetes mellitus, both of which are associated with an increased risk for atherosclerosis." (PMID 22927708, 2012). "During the recent years, there is a mounting evidence that apelin has pleiotropic effects on lipid and glucose metabolisms and therefore is correlated with metabolic disorders including diabetes." (PMID 23316219, 2012). "Several studies in patients with CKD and diabetes have reported disturbances in apelin function." (PMID 41515992, 2025). "This suggests that there may be a relationship between apelin and T2D that goes beyond the pathophysiology of diabetes itself." (PMID 41515992, 2025). "Circulating apelin levels have been studied in people with diabetes." (PMID 41515992, 2025). "The results from this study suggest that Apelin could be beneficial in not only managing but also potentially preventing CAD in patients with risk factors such as hypertension and diabetes." (PMID 39859178, 2025). "Apelin signaling system is tie up with a range of physiological responses, which is known to contribute to multiple pathological conditions, notably cardiovascular disorders and diabetes." (PMID 39538244, 2024). "The increased systemic apelin concentrations in diabetes and obesity could represent a compensatory mechanism for the reduced insulin sensitivity in T2DM." (PMID 39409058, 2024). "According to previous studies, diabetics may also demonstrate apelin resistance similar to insulin or leptin resistance." (PMID 38178017, 2024). "Moreover, it appears that apelin has a major function in disorders such as diabetes mellitus, fetal growth abnormalities, fetal hypoxia, and preeclampsia." (PMID 39457235, 2024). "Because of these relations, it was suggested that apelin may act as an insulin-sensitizing agent and may be a potential target for the treatment of diabetes, given its effective activity in energy metabolism and insulin sensitivity improvement." (PMID 37930396, 2024). "A recent study looked at serum levels of apelin in diabetes and/or periodontitis patients." (PMID 36902162, 2023).
diabetes (continued). "In our study, we used a type 1 diabetes mouse model, and our results demonstrated that despite the presence of tissue ischemia, diabetes prevented the basal expression of APJ/apelin in the adductor muscle and lowered plasma apelin concentrations compared to nondiabetic mice." (PMID 37636297, 2023). "Emerging evidence supports the role of apelin in the pathogenesis of diabetes." (PMID 37424869, 2023). "The apelin system has a role in glucose and lipid metabolism and may be a therapeutic target for obesity and type 2 diabetes mellitus." (PMID 37956047, 2023). "It appears that apelin plays a role in promoting DR in people with diabetes." (PMID 37828117, 2023). "Several studies reported variations in apelin plasma concentrations in the context of diabetes." (PMID 37636297, 2023). "However, since VEGF therapy showed promising results in preclinical studies but was unsuccessful in clinical trials, it remains to be proven if apelin treatment can be an effective therapy for patients with diabetes and PAD." (PMID 37636297, 2023). "It is suggested that apelin also has anti-diabetic features and may be used as a therapeutic agent for type I and II diabetes." (PMID 38203346, 2023). "Therefore, such apelin analogues, and particularly longer-acting forms such as pGlu(Lys8GluPAL)apelin-13 amide have exciting potential in the future of diabetes therapy." (PMID 35177945, 2022). "Furthermore, apelin participates in the pathology of diabetes by playing a pivotal role in increasing glucose uptake and insulin sensitivity." (PMID 35663309, 2022). "The apelin–APJ system is involved in diabetes-induced endothelial dysfunction and angiogenesis." (PMID 35355561, 2022). "First, lower plasma apelin levels in patients with OHCM compared with those in control subjects may be confounded by hypertension or diabetes, which were only in patients group." (PMID 35783816, 2022). "Diabetes-related diseases can be improved by apelin administration." (PMID 35355561, 2022). "In children with type 1 diabetes mellitus, the serum apelin level has a positive correlation with the carotid intima–media thickness, which indicates that serum apelin might be used as a predicting factor for atherosclerosis." (PMID 35355561, 2022). "Notably, these studies included patients with comorbidities (coronary artery disease, diabetes, heart failure) that are recognized to affect the apelin system." (PMID 35748053, 2022). "Therefore, the apelin–APJ system is a potential therapeutic target in diabetes and its complications." (PMID 35355561, 2022). "However, despite these discrepant findings, there is a general consensus that apelin isoforms improve metabolic status, suggesting clear potential for diabetes therapy." (PMID 35177945, 2022). "Besides these, long-term apelin administration significantly improves pancreatic islet mass and insulin level in diabetes." (PMID 35355561, 2022). "Multivariable logistic regression analysis indicated that serum apelin (OR = 0.304, 95%CI: 0.104–0.886, P = 0.029), as well as education levels, diabetes duration, cardiovascular disease, serum HbA1c, HDL-C, creatinine, and BDNF, were independent risk factors of MCI in patients with T2DM." (PMID 35610700, 2022). "In conclusion, apelin might reduce microvascular dysfunction induced by diabetes mellitus via improving endothelial dysfunction dependent on APJ activated NFκB pathways." (PMID 33504680, 2021). "In patients with melanoma, the following co-morbidities were also studied, as they might influence the circulating apelin levels: arterial hypertension, cardiovascular diseases, diabetes, asthma, inflammatory diseases, renal diseases." (PMID 33707612, 2021). "The association between apelin levels, glucose concentrations, and insulin sensitivity provided evidence that apelin may have a role in the pathogenesis of diabetes mellitus type 2 (DMT2)." (PMID 33540682, 2021). "The role of apelin in kidney disease in type 2 diabetes mellitus (DKD) is controversial." (PMID 34206927, 2021).
diabetes (continued). "Raised apelin levels were found in both insulin-resistant mice and type 2 diabetes mellitus patients (Xu, Tsao & Yue, 2011), which supported the speculation that insulin can stimulate APLN secretion." (PMID 33240613, 2020). "Furthermore, the dysfunction of the apelin-APJ system in diabetes and cardiovascular disorders induced reduction and increment of vasodilatation and vasoconstriction responses, respectively." (PMID 32908933, 2020). "Hence, the upregulation of Sirt3 induced by Apelin gene therapy has been shown to prevent heart failure by increasing autophagy in patients with diabetes." (PMID 32265695, 2020). "In addition to the protective role of apelin in heart failure and diabetes, it has been reported that apelin induced nitric oxide-dependent vasodilation in humans." (PMID 32517197, 2020). "It’s necessary to further clarify the role of VEGF, apelin, and HO-1 in patients with diabetes." (PMID 32770964, 2020). "Cardiac hemodynamic for the diabetes ischemia reperfusion injury rat models after Apelin therapy." (PMID 33342766, 2020). "Mounting evidence suggests that Apelin acts as an important adipokine against diabetes." (PMID 32265695, 2020). "Additionally, apelin-13 treatment ameliorated diabetes-induced reduction in islet mass and insulin content in Akita mouse which is a mouse model for ER stress-induced diabetes." (PMID 32517197, 2020). "Moreover, apelin levels in diabetes patients have a direct relationship with the amount of physical activity." (PMID 32908933, 2020). "Immunohistochemistry, qRT-PCR, and Western blotting assays revealed that the aorta of the Type 2 diabetes mellitus (T2DM) rat models had a high expression of apelin, PIO could decrease the expression of apelin in the PIO-treated rats." (PMID 31829402, 2019). "The association between apelin-APJ system genetic polymorphisms and apelin-36, fasting plasma glucose and diabetes mellitus was nonsignificant." (PMID 31217908, 2019). "Apelin has been highlighted as a naturally occurring peptide which inhibits insulin secretion, decreases glucose levels, increases insulin sensitivity and has a role in the pathogenesis of diabetes related complications." (PMID 31492821, 2019). "Secreted by adipose tissue apelin might contribute to obesity-related disorders and diabetes mellitus." (PMID 29875677, 2018). "Moreover, we have explored the potential mechanisms by which Sirt3 regulates APLN-induced myocardial angiogenesis in diabetes." (PMID 25311234, 2015). "This study further explored the potential mechanisms by which apelin may reduce cardiac injury in Postmyocardial infarction (MI)) model of diabetes." (PMID 29167823, 2015). "Moreover, we have explored the potential mechanisms by which apelin regulates myocardial autophagy in diabetes." (PMID 29167823, 2015). "Apelin induces angiogenesis in post-myocardial infarction of diabetes." (PMID 26342945, 2015). "Interestingly, plasma apelin has been shown to be a novel biomarker for predicting diabetes in Han Chinese subjects." (PMID 25914650, 2015). "Apelin is a novel adipocytokine participating in diabetes, but its role in diabetic retinopathy (DR) is unknown." (PMID 23874984, 2013). "Thus, we sought to investigate the relationship between APLN tagging SNPs and hypertension in a community-based population free of diabetes, excluding the confounding effect of diabetes on hypertension." (PMID 23316219, 2012). "Therefore, it appears that apelin levels increase in the presence of diabetes and CKD." (PMID 41515992, 2025). "Among obesemales without diabetes, apelin levels were significantly increased following 8 weeks ofaerobic training, and in adult patients with T2D, active as opposed to sedentarylifestyle was associated with higher apelin levels." (PMID 41585414, 2025).
diabetes (continued). "Indeed, exogeneous administration of apelin lowered blood glucose levels in normal weight and obese insulin-resistant mice, thereby shedding light at the potential therapeutic implications of apelin in metabolic diseases such as type 2 diabetes mellitus (T2DM)." (PMID 38806473, 2024). "Finally, experimental evidence suggests that SARS-CoV-2 induces cardiorenal injury in rats with post-myocardial infarction heart failure and mice with AKI and diabetes by downregulating apelin and ACE2, while upregulating SGLT-2, endothelin-1, and pro-inflammatory cytokines." (PMID 38448675, 2024). "Given that Apelin has been shown to interplay with caveolin in cardiomyocytes, it is possible that apelin may interact with adiponectin via caveolin in the context of myocardial I/R injury in diabetes, although further study is needed to test this hypothesis." (PMID 39538244, 2024). "However, the relationship between diabetes and apelin plasma levels remains to be clarified." (PMID 37636297, 2023). "However, there are conflicting reports about the apelin level in diabetes." (PMID 35355561, 2022). "Therefore, it is hypothesized that apelin might be involved in alleviating endothelial cell dysfunction and followed cardiomyopathy in diabetes mellitus." (PMID 33504680, 2021). "Therefore, previous exercise and apelin tests were conducted on subjects with diabetes or disease." (PMID 30696454, 2019). "While the role of apelin in improving insulin resistance by enhancing glucose utilization by muscle and fat is clear, its direct ability to protect muscles from diabetes-induced atrophy deserves further studies, but its elevated expression upon aerobic exercise is of note." (PMID 30984014, 2019). "In this study, we investigated the relationship between Apelin-13 level and BMD as well as other parameters to determine the influence of Apelin-13 on osteoporosis in patients with Type-2 diabetes mellitus, which may provide some clinical evidences for physicians in preventing osteoporosis." (PMID 29643899, 2018). "In addition, apelin serum level was found to be decreased in human with primary hypertension, coronary artery disease, advanced heart failure, and increased in type 2 diabetes mellitus and impaired glucose tolerance subjects." (PMID 29721104, 2018). "Moreover, dysfunctional endothelium-dependent vasodilation and impaired nitric oxide bioavailability have been reported in diabetes, raising the possibility that apelin may interact with diabetes in the regulation of blood pressure." (PMID 23316219, 2012). "Moreover, after surgery, they could observe a significant decrease of apelin levels only in the morbidly obese subjects with impaired fasting glucose or diabetes, a decrease that followed the changes in blood glucose and insulin sensitivity." (PMID 23227256, 2012). "Apelin can maintain β-cell identity in mice in the HFD and STZ models of diabetes, ensuring maintenance of β-cell mass, and also contributes to a decrease in apoptosis and to increased β-cell proliferation." (PMID 39045459, 2024). "Further assessment with IPA identified enrichment in key signaling pathways, including apelin and SNARE signaling (diabetes) and semaphorin and Rho signaling (hypertension)." (PMID 36902363, 2023). "Recent reports in patients with type 2 diabetes mellitus manifested the expression of tight junction markers, including GJA1, was significantly suppressed by hyper-activating Apelin (APLN) peptide and downregulated in diabetic testis." (PMID 38390397, 2023). "To identify the anti-EndMT and antifibrosis effect of apelin in vivo, we established the apelin-treated streptozotocin- (STZ-) induced diabetic mouse model." (PMID 36785790, 2023). "Following 28 days of femoral artery ligation, we observed that diabetes reduced mRNA expression of both APJ and apelin in the ischemic muscle by 60% (P = 0.0207) and 67% (P = 0.0055), respectively." (PMID 37636297, 2023).